GPC3 (glypican 3)
Diseases named in the same sentence as GPC3 in open-access papers (continued):
Sharing a sentence is not in itself a finding about the gene and the disease.
liver cancer (continued). "GPC3 is often found in high amounts on liver cancer cells but is rare in healthy liver tissue." (PMID 38792650, 2024). "initially reported increased expression of GPC-3 in primary liver cancer." (PMID 39935848, 2024). "Clusters 1, 2, 3, 5, and 6 represented genes that were highly expressed in stages of embryonic development, but were expressed at low levels in adult livers, including oncofetal genes Afp, Gpc3, Sall4 (cluster 2), H19 (Cluster 3) and Igf2 (Cluster 5), which are re-expressed in liver cancer." (PMID 38225233, 2024). "Due to its high tumor-to-liver ratio, GPC-3 is also ideal for targeted imaging in liver cancer." (PMID 39404428, 2024). "Furthermore, it has been reported to interact with glypican 3 (GPC3) in liver cancer cells, leading to activation of insulin-like growth factor 1 receptor (IGF1R) signaling, which is involved in tumorigenesis." (PMID 37241771, 2023). "In order to further verify the causal relationship between air pollution and primary liver cancer, we selected four biomarkers (Alpha-fetoprotein, Osteopontin, Glypican-3 and Arginase-1) which are closely related to primary liver cancer as the outcome and conducted MR Analysis again." (PMID 37575092, 2023). "To elucidate the functions of the three cell types, we first evaluated the target-mediated CAR-dependent cytokine production of iCAR-TCTL and iCAR-TILC by co-culturing the cells with SK-Hep-1 (a liver cancer cell line) transduced with GPC3 (SK-Hep-GPC3) as a stimulator." (PMID 36509913, 2023). "used Logic-gated(Log) GPC3-synNotch-inducible CD147-CAR to target liver cancer cells." (PMID 36761757, 2023). "Further research may be needed to validate these findings and to explore other factors that may contribute to the sensitivity of GPC3 as a biomarker for liver cancer." (PMID 37046471, 2023). "Furthermore, some of them have been proven to be drug targets in solid tumors, such as GPC3 in liver cancer, MSLN in gastric cancer, and EGFR in glioma." (PMID 36428765, 2022). "Finally, to verify that GPC3 is a highly specific biomarker for liver cancer, we used human tissue samples for verification." (PMID 35331259, 2022). "Therefore, GPC3 is a highly specific biomarker with clinical potential for the diagnosis of liver cancer." (PMID 35331259, 2022). "Therefore, we concluded that the bispecific CAR-T cell and combined CAR-T cell strategies significantly improved the activity of CAR-T cells in liver cancer by targeting PD-L1 and GPC3." (PMID 35317524, 2022). "Our previous study developed GPC3-targeted CAR-T cells as an emerging liver cancer therapy." (PMID 35317524, 2022). "The new Glypican-3-targeted, curcumin-loaded microbubbles with increased drug loading capacity have excellent targeting capabilities for specific HepG2 cells used for sonodynamic therapy in liver cancer." (PMID 34154581, 2021). "Sono-photodynamic treatment with Glypican-3-targeted, curcumin-charged microbubbles may be a promising route for the treatment of liver cancer." (PMID 34154581, 2021). "It has the ability to specifically target liver cancer cell and the anti-GPC3 Ab were combined with nanoparticles (NPs), an AB-SFB-NP nano-drug delivery system with large drug loading capacity, good targeting, high safety, stable, and controllable drug release rate in the tumor was constructed." (PMID 34923912, 2021). "To improve early detection, and therefore treatment and prognosis of liver cancer patients, we have developed an imaging probe for positron emission tomography, targeting a protein, glypican-3, which is specifically expressed at high levels in liver cancer cells." (PMID 34439132, 2021). "In addition to GPC3, most gene signatures used in our diagnosis model have also been confirmed in liver cancer, and the expression trends of those genes are consistent with our DP.eHCC model." (PMID 32849835, 2020). "Glypican-3 (GPC-3) protein is considered as a candidate therapeutic target in hepatic cancer." (PMID 33126630, 2020).
liver cancer (continued). "However, the authors concluded that naked anti-GPC3 antibodies are insufficient to cure liver cancer in mice and humans." (PMID 32575828, 2020). "Importantly, we found significant upregulation of hepatic cancer marker transcripts, including Afp, Golm1, Tgfb, Gpc3, Villin, and Ki67." (PMID 33110211, 2020). "To further confirm that the miPS-Huh7cmP1 cells were enriched with the cells expressing liver cancer-associated markers (AFP, GPC3 and CK19) and CSC markers (CD44, CD133 and CD24), we examined the gene expression levels compared to those in miPSCs and miPS-Huh7cm cells." (PMID 32203212, 2020). "Since GPC3 was revealed as a new marker of liver cancer in 1997, its biological function and expression pattern have been gradually identified, and it has evolved from a potential tumor marker to an important indicator for clinical detection, and a series of GPC3 target therapies has been developed." (PMID 32127929, 2020). "Finally, by using the same strategy, we prepared a new CIRP-based vaccine containing glypican-3, human antigen commonly found in patients with liver cancer." (PMID 33207844, 2020). "Imaging examinations (e.g., ultrasound imaging (UI), computer tomography (CT) imaging, and magnetic resonance imaging (MRI)) and serum measurements (e.g., alpha-fetoprotein (AFP) and glypican-3 (GPC3)) are the most commonly used methods for early screening and diagnosis of liver cancer." (PMID 32293343, 2020). "Materials and Methods: We synthesized variants of two previously published peptides, DHLASLWWGTEL (TJ12P1) and RLNVGGTYFLTTRQ (L5), and evaluated their in vitro binding performance in paired isogenic cell lines, A431(GPC3−) and A431-GPC3+ (G1), as well as the liver cancer cell line HepG2." (PMID 31424293, 2019). "In contrast, hepatic cancer cells, from rats transplanted with sheets fabricated from HepG2 –BM-MSCs, HepG2 –UC-MSCs and by HepG2 alone, showed a highly membranous pattern of staining with GPC3." (PMID 28850615, 2017). "GPC3 silencing by small interfering RNAs (siRNAs) or miRNAs inhibits hepatic cancer cell growth." (PMID 28476031, 2017). "Several microRNAs negatively regulating GPC3 have been described in liver cancer cells." (PMID 28476031, 2017). "Interestingly, GPC3 level is more frequently elevated than AFP level (88% versus 55%) in patients with liver cancer, and especially in those with HCC tumors < 3 cm (77% versus 43%)." (PMID 27655712, 2016). "In addition, PD-1 blockade increased the number of GPC3-specific CTLs, which degranulate against liver cancer cell lines." (PMID 25354479, 2015). "Furthermore, PD-1 blockade enriched the population of GPC3-specific CTLs that degranulated against only GPC3-positive liver cancer cell lines (SK-Hep1/vec pulsed with GPC3144–152 peptide, SK-Hep1/GPC3 and HepG2)." (PMID 25354479, 2015). "The phase I clinical trial using GPC3 for liver cancer is ongoing." (PMID 22606345, 2012). "Taken our results together with their findings, GPC3 expression in liver tumor tissues may reflect the abundance of liver cancer stem cells, which may have a prognostic value for HCC patients." (PMID 22606345, 2012). "Additionally, it was shown that GPC3 was highly expressed in CD90+CSCs in liver cancer cell lines and human tumor tissues, implicating that GPC3 is a specific marker for liver CD90+CSCs." (PMID 22606345, 2012). "In our present study we also found a positive correlation between GPC3 expression and the number of CD90+CSCs present in the liver tumor tissues, suggesting that GPC3 expression could indicate the amount of liver cancer stem cells in tumors." (PMID 22606345, 2012). "How GPC3’s structural features determine its pro-oncogenic roles has been relatively extensively investigated via utilizing various GPC3 mutants, especially in liver cancer and the activation of Wnt signaling, one of the vital mechanisms underlying its oncogenic role." (PMID 40422229, 2025).
liver cancer (continued). "MR Analysis of air pollution and primary liver cancer related tumor markers AFP, OPN and GPC-3 found no causal association, further confirming our previous conclusion that there was no statistical association between air pollution and primary liver cancer risk." (PMID 37575092, 2023). "Our recent study proved that fusion of HN3(an excellent affiliative antibody for GPC3) with exosomes derived from epithelial cells could advance liver cancer cell targeting specificity and thus could positively enhance the anti-cancer effect of sorafenib on GPC3 over expressed liver cancer cells." (PMID 37202772, 2023). "Therefore, GPC-3 can be used as an important immunotherapy target for liver cancer." (PMID 37920165, 2023). "GPC3 also promotes the growth of liver cancer cells and may regulate the TGF-β signaling pathway." (PMID 35671267, 2022). "Therefore, when diagnosing liver cancer, the combined use of GPC3 and AFP may make the diagnosis more reliable." (PMID 34200243, 2021). "Thus, Glypican-3 is becoming a promising candidate for liver cancer diagnosis and immunotherapy." (PMID 32127929, 2020). "Thus we hypothesized that fusing of human antibody HN3 with epithelial cell-derived exosomes can improve its tumor targeting efficiency as GPC3 is specifically over expressed in liver cancer cells." (PMID 33062407, 2020). "GPC-3 is a transmembrane heparan sulfate proteoglycan that regulates cell growth by tissue-dependent cellular signaling; as its expression is increased in liver cancers, it has been used as a tumor maker and currently in ex vivo gene therapy to modify CAR-T to target HCC." (PMID 31769427, 2019). "Therefore, we speculate that miR-4510 plays a major role in the deregulation of GPC3 in liver cancer." (PMID 28476031, 2017). "In the most recent study, an immunotoxin composed of an anti-Glypican-3 (GPC3) antibody and Pseudomonas aeruginosa exotoxin A (PE38) was designed for the treatment of SCLC and liver cancer." (PMID 40177519, 2025). "Another research on Interleukin-15-armored GPC3-CAR T cells for solid tumors, including liver cancer, showed that IL15 increases the expansion, intratumoral survival, and antitumor activity of GPC3-CAR-T cells in patients." (PMID 40308592, 2025). "The XCL1-Glypican-3 fusion gene has been developed as a cancer vaccine, showing promise in enhancing the generation of GPC3-specific CD8+ T cells, delaying liver cancer growth and improving the efficacy of anti-PD-1 therapy." (PMID 41426973, 2025). "Few months later, for liver cancer management, cationic switchable LNPs encapsulating Sorafenib (SRF) and anti-miRNA27a, decorated with anti-GPC3 antibodies, were designed." (PMID 40880603, 2025). "We sought to combine GPC3 detection with multi-biomarker panels to enhance sensitivity and specificity in early-stage HBV-, HCV-, and ALD-related liver cancer diagnosis." (PMID 41471145, 2025). "Various molecules, such as GPC3, c-Met, and NKG2D, show significant promise as potential immunotherapeutic targets in liver cancer." (PMID 39569202, 2024). "Within this panel, we find previously documented liver- and liver cancer-relevant marker gene ligands SERPINC1 and GPC3 LRIs to be specific and unique to liver cancer blood samples and thus serve as potentially potent biomarkers." (PMID 39850635, 2024). "Alpha-fetoprotein (AFP), Osteopontin (OPN), Glypican-3 (GPC-3) and Arginase-1 (Arg-1) are common primary liver cancer related biomarkers." (PMID 37575092, 2023). "Gpc3 has been reported to modulate WNT and HH signaling in liver cancer and interestingly, GPC3 was previously found to interact with BMP2, like the not differentially expressed GPC1, to regulate suture fusion." (PMID 37378024, 2023). "This is a promising sign of our ongoing work, utilizing DEXs to bind with short peptides of liver cancer-specific AFP and GPC3 that can more specifically activate T lymphocytes for prevention or targeted therapy of liver cancer." (PMID 37631284, 2023).
liver cancer (continued). "Similar results were obtained from knockdown experiments in another liver cancer cell line, HuH7, indicating that E-Syt1 contributes to the activation of IGF1R-Erk1/2 signaling in GPC3-positive liver cancer cells." (PMID 37241771, 2023). "Some VHHs for both GPC3 and HER2 bind to their target liver cancer cell hepG2 and breast cancer cell SK-BR-3, respectively." (PMID 35225868, 2022). "The examination of GPC3 and AFP in blood samples is currently used for the diagnosis of patients with liver cancers." (PMID 36551548, 2022). "Although plenty of tumor antigens have been found in liver cancer, only the vaccines targeting AFP, GPC3 and MRP3 show good tolerance and safety, and the specific T cell response rate of these vaccines exceeds 70%." (PMID 34513678, 2021). "In liver cancer diagnosis, AFP is a traditional biomarker, and the expression of GPC3 can distinguish benign nodular liver tumor with AFP negative." (PMID 34200243, 2021). "Meanwhile, the use of exosomes in studying the 4 serum markers of liver cancer (AFP, AFP-L3, GP73, and GPC3) has rarely been reported." (PMID 31901224, 2020). "Wang and his colleagues, (2018), correlated GPC3 expression with liver cancer differentiation in HCC patients and reported that GPC3 promoted HepG2 cells proliferation through the hedgehog pathway." (PMID 33076548, 2020). "Immuno-reactive liver cancer markers AFP, GPC3 and CK19 were positively stained as well as the CSC markers such as CD44, CD24 and CD133 in the tumour tissue developed in the liver." (PMID 32203212, 2020). "As an authentic example, doxorubicin is a chemotherapeutic agent used for the treatment of liver cancers and exhibited hydrogen bond interactions with TYR255, CYS401 and PRO267 respectively of GPC-3 protein." (PMID 33126630, 2020). "An array of numerous alternative yet costly tumor markers have been proposed to screen liver cancer, including Golgi protein 73 (GP73), glypican-3 (GPC-3), protein induced by vitamin K absence or antagonist-II (PIVKAII), and some MicroRNAs." (PMID 32190001, 2020). "In exploring the biological role of GPC3 in liver cancer (HCC) cells, GPC3 was found to promote HepG2 cell proliferation through Hh signaling." (PMID 31428581, 2019). "The potential of GPC3 as a disease biomarker needs further study in different diseases in particular in lung diseases, such as ARDS, and in cancers including lung and liver cancer." (PMID 28510121, 2017). "Flow cytometry indicated that GPC3 was highly expressed in liver CD90+CSCs and mature cancer cells in liver cancer cell lines and human liver tumor tissues." (PMID 22606345, 2012). "Furthermore, given that GPC3 and CK19 are commonly used prognostic markers in clinical liver cancer diagnostics, we also conducted IHC staining for these markers on HCC tissue chips and scored them accordingly." (PMID 40458412, 2025). "We also identified a proliferative cluster, which mainly consisted of proliferating T cells and a large cluster of HCC cancer cells (40%) expressing both genes associated with normal liver function (ALB, HP, FGA, FGB) and liver cancer (AFP, SPINK1, GPC3, AKR1C1)." (PMID 38030622, 2023). "An increasing number of methods can help the evaluation, including HBV virus copy number, glypican 3, heat shock protein 70, glutamine synthetase, staging systems such as Barcelona Clinic Liver Cancer (BCLC) and China Liver Cancer Staging (CNLC) as well as imaging examinations." (PMID 37845287, 2023). "GPC-3 negative liver cancer cells were significantly more sensitive to cabozantinib than GPC-3-positive cells." (PMID 35127582, 2022). "Here, we found that high-level expression of GPC3 coincided with that of FAT1 in all the tested liver cancer cell lines (HepG2, Hep3B, and Huh7), and undetectable in normal liver tissues." (PMID 33420124, 2021). "GPC3 overexpression in liver cancer has been frequently reported without debate; however, its expression pattern in NSCLC remains debatable." (PMID 34112123, 2021).
liver cancer (continued). "In addition, Glypican 3 (GP3) is highly related to the appearance and development of liver cancer, is used for diagnosis, and is an important target for HCC immunotherapy." (PMID 34574650, 2021). "We also detected a clear upregulation of several liver cancer marker genes such as AFP, GPC3, SAA1, and VIL1 in transformed iHeps and in CMT + sgTP53 tumors compared to control fibroblasts; AFP was also found among the most enriched genes in both CMT + sgTP53- and CMT-transformed iHeps." (PMID 34302118, 2021). "An anti-GPC1 monoclonal antibody has shown potent antitumor activity in esophageal squamous cell carcinoma, whereas a human monoclonal antibody against GPC3, HS20, destroying Wnt3a and GPC3 interaction and subsequent signaling, exhibits elevated antitumor activity in liver cancer." (PMID 32916872, 2020). "ADCs containing GPC3 or CD24 antibodies may provide a more accurate and effective way of treating liver cancer, especially when systemic therapy is combined with locoregional trans-arterial administration directly into the vicinity of the HCC." (PMID 32575828, 2020). "Moreover, prolonged MB109 treatment suppressed the expression of five prominent liver cancer stem cell (LCSC) markers, including CD44, CD90, AFP, GPC3 and ANPEP." (PMID 27650540, 2016). "Taken together, our study suggests that GPC3 is involved in HCC cell migration and motility through HS chain-mediated cooperation with the HGF/Met pathway, showing how HS targeting has potential therapeutic implications for liver cancer." (PMID 26332121, 2015). "In this study, we showed that GPC3 did not have a regulatory role in cell proliferation of liver cancer stem cells." (PMID 22606345, 2012). "Taking the results of these functional studies together, we suggest that GPC3 is not involved in regulating the studied properties of liver cancer stem cells." (PMID 22606345, 2012). "Regardless of its ambiguous functional roles on HCC, GPC3 is a potential target gene for liver cancer therapy because it is highly expressed in HCC but is absent in normal liver tissues." (PMID 22606345, 2012). "Stable GPC3-knockout in liver cancer cell lines (HepG2, Hep3B, Huh7) and ectopic GPC3 expression in GPC3-negative liver cancer cells (SNU449), as well as in non-hepatic A431 cells, demonstrated that GPC3-mediated radioresistance is not restricted to hepatic lineage." (PMID 42182336, 2026). "A recent clinical study in adults with liver cancer demonstrated that GPC3-directed CAR T cells co-expressing IL-15, but not GPC3 CAR T cells alone, achieved a disease control rate of 66.7% (8 of 12 patients) and an objective response rate of 33.3% (4 of 12 patients)." (PMID 40684183, 2025). "One possible explanation for the results may be that GPC3 is more effective than AFP in detecting early-stage liver cancer and is not correlated with tumor size." (PMID 37046471, 2023). "This indicates that GPC3 is expressed in liver cancer cells but not in normal liver cells." (PMID 35331259, 2022). "In well-differentiated HCC tissues, the degree of positive expression of GPC3 in liver cancer cells was significantly higher than that of non-tumor cells around the lesion, and GPC3 was not expressed in the pathological tissues of focal nodular hyperplasia by immunohistochemical staining." (PMID 34923912, 2021). "The mechanism of GPC3 in the process of liver cancer has not been thoroughly explained." (PMID 32127929, 2020). "However, the GPC3 peptide vaccine did not prevent the occurrence of liver cancer in STAM mice C57BL/6N-NASH (data not shown)." (PMID 23354275, 2013). "Based on our current findings, regardless of ambiguous roles of GPC3 on liver cancer stem cells, GPC3 could be a promising target gene for HCC immunotherapy owing to its specificity on the liver cancer stem cells, and its absence in normal liver stem cells." (PMID 22606345, 2012).